PTH (parathyroid hormone)
Diseases named in the same sentence as PTH in open-access papers (continued):
Sharing a sentence is not in itself a finding about the gene and the disease.
Hypocalcemia (continued). "Clinical hypoparathyroidism, a combination of lower PTH values and symptoms and/or signs of hypocalcemia, was recorded in 31 patients, both on the day of the surgery and the first postoperative day, respectively." (PMID 38322433, 2024). "HPT-III occurs when the chief cells of the parathyroid glands secrete excess PTH to balance their function and respond to chronic hypocalcemia." (PMID 39152506, 2024). "The ameliorated increase in PTH secretion in conditions of hypocalcemia can, therefore, be attributed to the artificial introduction of FGF-23 in the milieu of normal cells." (PMID 38785509, 2024). "POD1 PTH values correlated better with hypocalcaemia symptoms (r = 0.799 vs 0.466) and signs (r = 0.815 vs 0.392) compared to calcium levels." (PMID 39649119, 2024). "Hypocalcemia stimulates the release of PTH, which partially corrects hypocalcemia but increases urinary P excretion, leading to hypophosphatemia." (PMID 38732596, 2024). "Supplements were later reinstated in an additional three patients (2.9 per cent) who had hypocalcaemia and low PTH levels more than 24 months after surgery, although they had no treatment 12–24 months after surgery." (PMID 37995259, 2024). "Both day 1 PTH and a drop in PTH predicted day 1 hypocalcaemia (p < 0.001) and 6-month hypoparathyroidism (p < 0.001)." (PMID 38478048, 2024). "Surprisingly, the patient also exhibited significant hypocalcemia, hyperphosphatemia, and low parathyroid hormone levels, which led to the diagnosis of primary hypoparathyroidism, an unusual finding in the context of sarcoidosis." (PMID 39416579, 2024). "Biochemical evaluation at several ages revealed persistent hypocalcemia, high normal phosphorous, and inappropriately low normal PTH before proper treatment initiation." (PMID 39797201, 2024). "•Concentrations of PTH are stabilized by 5 to 15 days in milk in response to induced subclinical hypocalcemia." (PMID 39650027, 2024). "FIH can also be caused by an activating pathogenic variant in the calcium sensing receptor (CASR); inappropriate activation of this sensor signals Ca sufficiency even during hypocalcemia, thereby suppressing PTH secretion." (PMID 39439810, 2024). "In our patient, a significant rise in PTH levels was observed, likely as a compensatory response to severe hypocalcemia." (PMID 39639476, 2024). "ROC curves were used to study the relationship between PTH levels, on the one hand, and transient hypocalcaemia and 6-month PoSH, on the other hand." (PMID 38478048, 2024). "We describe a patient used PPI with hypomagnesemia showed normal parathyroid hormone (PTH) despite hypocalcemia and reversible delirium." (PMID 39465769, 2024). "Preoperative control of risk factors and improvement of surgical techniques to prevent intraoperative PTH decreases represent the two main approaches to preventing hypocalcemia after total thyroidectomy." (PMID 38803480, 2024). "Homozygous Atp2b1 knockout (ko) mouse is embryonically lethal before organogenesis, whereas heterozygous Atp2b1-ko mice have hypertension, hypocalcemia with decreased intact parathyroid hormone (PTH) levels, and increased bone mineral density." (PMID 37926713, 2024). "These patients display hypocalcemia, inappropriately low PTH levels, and abnormalities of bone, eyes, and head." (PMID 38697929, 2024). "In our cohort, we had information on PTH at the time of hypocalcaemia in less than half of the patients." (PMID 38308768, 2024). "Here, we report a case of a newborn with Sanjad-Sakati syndrome who had severe hypocalcemia since birth who responded to PTH subcutaneous pump infusion." (PMID 38655381, 2024). "For day 1 hypocalcaemia, the area under the curve (AUC) for day one PTH was 0.729, whereas that for drop in PTH was 0.726." (PMID 38478048, 2024). "Decreased 1,25(OH)2D secretion also results in reduced intestinal calcium absorption, leading to hypocalcemia and increase in PTH levels." (PMID 39666728, 2024).
Hypocalcemia (continued). "The biochemical profile revealed hypocalcemia, hyperphosphatemia, along with high PTH levels and normal vitamin D levels, resembling pseudohypoparathyroidism." (PMID 39351120, 2024). "In one of these siblings who suffered from severe resistant symptomatic hypocalcemia, treatment with recombinant PTH (Teriparatide) resulted in normalization of serum calcium and phosphate with resolution of symptoms." (PMID 39435356, 2024). "PTH subcutaneous infusion can be highly effective in refractory hypocalcemia cases and can significantly impact the treatment course and facilitate hospital discharge as seen in our case." (PMID 38655381, 2024). "Serum calcium measured on the first postoperative day had the highest sensitivity (94%) in predicting the occurrence of hypocalcemia on the fifth postoperative day, while PTH measured one hour after surgery had the highest specificity (89%)." (PMID 38322433, 2024). "It is well-known that after the induction of sustained hypocalcaemia, preformed PTH is secreted into the blood within 1 min and restoration of normocalcaemia results in a decrease in PTH levels with an apparent half-life of approximately 3 min." (PMID 38566240, 2024). "The value of PTH in predicting post-thyroidectomy hypocalcaemia has been investigated extensively and reported in the literature." (PMID 39649119, 2024). "The decreased biologically active Vit D leads to decreased calcium absorption in the gut, resulting in hypocalcemia and increased circulating PTH." (PMID 39279896, 2024). "In our family, both siblings and the mother had mild brachydactyly and all had mild PTH resistance but only the mother had hypocalcemia." (PMID 39104441, 2024). "Two patients (1 in each group) discontinued etelcalcetide due to excessive PTH suppression and 2 other patients (both in the standard group) stopped the drug because of hypocalcemia or gastrointestinal intolerance." (PMID 38344732, 2024). "We found that serum PTH levels had a better coefficient of correlation than serum calcium levels with both patient-reported symptoms and clinically elicited signs of hypocalcaemia." (PMID 39649119, 2024). "Despite efforts to mitigate hypocalcemia, the significant increase in PTH post-denosumab administration in our study suggests that mechanisms beyond hypocalcemia triggered this increase." (PMID 38592300, 2024). "In conclusion, this study shows that a single postoperative PTH value is sufficient in predicting both transient hypocalcaemia and postsurgical hypoparathyroidism." (PMID 38478048, 2024). "His workup suggested a diagnosis of PHP as the unifying explanation for obesity, short stature, round facies, orchiopexy, learning delays, hypocalcemia, and hyperphosphatemia with elevated PTH." (PMID 39193092, 2024). "The binary logistic regression model identified age, PTH, calcium, and ionized calcium on the day of surgery, and on the first postoperative day showing statistical significance in predicting symptomatic hypocalcemia on the fifth postoperative day." (PMID 38322433, 2024). "The mainstay preventive measure of postthyroidectomy hypocalcemia is avoiding injury to the parathyroid (PTH) gland during surgery." (PMID 38371915, 2024). "PTH resistance leads to a dysfunction of the phosphocalcic metabolism and is responsible for hypocalcemia and hyperphosphatemia." (PMID 39267114, 2024). "Although reduced PTH with hypocalcemia was observed in over 80% of individuals, representing the typical sign of KCS2, patients with normal PTH have also been described." (PMID 38591167, 2024). "Similar to PTH, 1,25(OH)2D plays a key role in correcting hypocalcemia by promoting Ca release from the bones, renal Ca reabsorption, and intestinal Ca absorption." (PMID 38803480, 2024). "The most sensitive predictor of symptomatic hypocalcemia present on the fifth postoperative day was PTH sampled on the first postoperative day." (PMID 38322433, 2024).
Hypocalcemia (continued). "In this study, the proband exhibited recurrent epileptic seizures, with biochemical analyses indicating classic signs of pseudohypoparathyroidism, including hypocalcemia, hypokalemia, and markedly elevated PTH levels." (PMID 39519162, 2024). "In this report, we describe a family with four affected siblings who were diagnosed for many years as cases of PHPT type 1b because they had chronic hypocalcemia and elevated levels of PTH." (PMID 39435356, 2024). "Recombinant human parathyroid hormone (rhPTH) has shown promising results in correcting hypocalcemia, but its widespread application is limited in China due to the need for daily injections and its high cost." (PMID 38483607, 2024). "Further evaluation of hypocalcemia revealed a very low level of intact parathyroid hormone (PTH) of 2 pg/mL." (PMID 38600559, 2024). "A male patient aged 11 years 10 months with obesity and mild developmental delay was found to have hypocalcemia, hyperphosphatemia, and an elevated parathyroid hormone level." (PMID 39193092, 2024). "The results showed that a decrease in 1,25(OH)2D concentration in the group with PTH levels above 15 pg/mL was the only significant factor for next-morning Ca concentration and hypocalcemia." (PMID 38803480, 2024). "Hypoparathyroidism is defined by hypocalcemia with inappropriately normal or low parathyroid hormone levels." (PMID 38578400, 2024). "POD 1 PTH levels of less than 10 pg/mL was noted in 71.4%, and 85.7% had signs and symptoms of hypocalcaemia." (PMID 39649119, 2024). "Further investigation revealed hypocalcemia and elevated parathyroid hormone (PTH) levels, leading to diagnosis of a parathyroid adenoma." (PMID 39109312, 2024). "The decline in renal function results in hypocalcemia, hyperphosphatemia, and reduced calcitriol levels, stimulating PTH synthesis and secretion while promoting parathyroid gland hyperplasia, leading to secondary hyperparathyroidism." (PMID 39606517, 2024). "Horses challenged with LPS had hypocalcemia with increased release of PTH that decreased urinary fractional excretion of Ca and Mg but increased urinary loss of P, the latter response possibly as an attempt to reestablish Ca balance." (PMID 38672379, 2024). "Secondary causes of elevated PTH levels include chronic kidney disease, where impaired kidney function leads to phosphate retention and hypocalcemia, subsequently stimulating the parathyroid glands to produce more PTH." (PMID 39200293, 2024). "PTH levels are the most common biochemical markers that are measured to predict postoperative hypocalcemia." (PMID 38646308, 2024). "Hypoparathyroidism (HypoPT) is a rare condition characterized by insufficient levels of parathyroid hormone (PTH), resulting in hypocalcemia, hyperphosphatemia, and hypercalciuria." (PMID 38741607, 2024). "Denosumab-induced hypocalcemia triggers PTH release, stimulating calcium release from bones, thereby raising serum calcium levels." (PMID 38181430, 2024). "The deficiency of active vitamin D affects theintestinal absorption of calcium, leading to hypocalcemia, which stimulatesthe parathyroid glands to secrete parathyroid hormone." (PMID 39076321, 2024). "It was found that a PTH value <10 pg/mL as this cutoff had a better sensitivity (79.5% vs 74.1%) than a cutoff of <15 pg/mL (AUC) in predicting POD 1 hypocalcaemia." (PMID 39649119, 2024). "The results of this study shed light on the complex interplay between VD metabolism, PTH regulation, and post-thyroidectomy hypocalcemia." (PMID 38803480, 2024). "Factors such as hypocalcemia, decreased serum levels of hydroxycholecalciferol (active form of vitamin D), increased serum levels of phosphate and parathyroid hormone can disrupt ameloblast activity." (PMID 40952865, 2024). "KCS and OCS are characterized by dysregulation in Ca2+ homeostasis, specifically hypocalcemia, low serum PTH, and skeletal abnormalities." (PMID 38697929, 2024).
Hypocalcemia (continued). "High PTH levels can indicate secondary hyperparathyroidism, which occurs in response to hypocalcemia and/or hypophosphatemia commonly seen in MBDP." (PMID 38951759, 2024). "The identification of lymph node metastasis, total thyroid surgery, decreased PTH and 25(OH)D3 levels, and albumin concentration proved to be instrumental in guiding the surgical team toward preventing the onset of hypocalcemia." (PMID 40071247, 2024). "Among all patients, 25% presented hypomagnesemia, 18.9% presented hypocalcemia, 2.1% presented hypophosphatemia, and 27.6% had high parathyroid hormone (PTH) levels." (PMID 38674789, 2024). "Persistently increased parathyroid hormone (PTH) levels and parathyroid hyperplasia are the characteristics of SHPT and are mainly caused by hypocalcemia, hyperphosphatemia, and vitamin D deficiency." (PMID 39697216, 2024). "Laboratory analysis showed hypokalemia, hypomagnesemia, and normal parathyroid hormone despite hypocalcemia, physical examination showed horizontal nystagmus and the brain MRI was negative." (PMID 39465769, 2024). "We identified 31 cases (37.8%) of hypocalcemia on the morning after surgery in the group with all 82 patients, 19 of 61 patients (31%) in the group with PTH >10 pg/mL, and 10 of 50 patients (20%) in the group with PTH >15 pg/mL." (PMID 38803480, 2024). "Studies have shown that a low recovery rate predicts postoperative PTH levels (< 12 pg/mL) with 100% sensitivity and 92% specificity for the development of hypocalcemia." (PMID 40071247, 2024). "Hypocalcemia is responsible for PTH stimulation, which leads to progressive recovery of serum calcium levels, but increases urinary phosphate loss." (PMID 39462348, 2024). "In conclusion, we demonstrated the important role of 1,25(OH)2D in preventing sudden, severe hypocalcemia due to decreased PTH levels after total thyroidectomy." (PMID 38803480, 2024). "Initial serum studies showed hypocalcemia, hyperphosphatemia, low parathyroid hormone (PTH), low vitamin A, and low zinc, with otherwise normal creatinine, albumin, magnesium, potassium, 25-hydroxy vitamin D, and vitamin E and K levels." (PMID 39411620, 2024). "The family study showed a brother with a similar condition and an inadequate PTH response to hypocalcemia in the father only suggesting an autosomal dominant inheritance." (PMID 39435356, 2024). "Postnatal growth retardation, cerebral calcification, seizures, eye and dental abnormalities, low parathyroid hormone and hypocalcemia can occur in both KCS types." (PMID 38591167, 2024). "A case of a newborn with this syndrome, presenting with hypocalcemia refractory to conventional treatment, was treated with subcutaneous infusion of recombinant PTH (teriparatide 250 mcg/mL)." (PMID 39246904, 2024). "Biochemical evaluation at several ages revealed persistent hypocalcemia, high normal phosphorous, and inappropriately low normal PTH." (PMID 39797201, 2024). "The identification of lymph node metastasis, total thyroid surgery, decreased PTH and 25(OH)D3 levels, and albumin concentration are crucial factors in guiding the surgical team to prevent the onset of hypocalcemia." (PMID 40071247, 2024). "Biochemically, it is characterized by hypocalcemia, hyperphosphatemia, normal vitamin D levels along with high PTH levels." (PMID 39351120, 2024). "The release of PTH is triggered by hypocalcemia and plays a crucial role in compensating for calcium deficiency, particularly after gastric bypass surgery, where the anatomical changes reduce calcium absorption in the gut." (PMID 39411620, 2024). "Hypoparathyroidism (HPt) is a rare endocrine disorder responsible for hypocalcemia and hyperphosphatemia due to insufficient levels of parathyroid hormone (PTH)." (PMID 38655382, 2024). "She had mild hypocalcemia with PTH resistance and normal TSH, IGF-1, and gonadotropins, and slightly raised HbA1c and hypercholesterolemia." (PMID 39104441, 2024).
Hypocalcemia (continued). "The aim of the study is to compare the drop in perioperative PTH to postoperative day 1 PTH in predicting hypocalcaemia and hypoparathyroidism." (PMID 38478048, 2024). "Active VD (calcitriol or alfacalcidol) and Ca would raise serum Ca to the upper limit of the normal range in a short period and lower PTH levels, both of which benefit postoperative hypocalcemia." (PMID 38803480, 2024). "Counteracting the stimuli for PTH increase—such as hypocalcemia, hyperphosphatemia, high phosphate intake, and vitamin D deficiency—are desirable as early as possible." (PMID 38893652, 2024). "Hypocalcemia, hyperphosphatemia, and decreased serum 1,25-dihydroxyvitamin D (1,25(OH)2D) can stimulate the secretion of PTH, while elevated serum calcium, 1,25(OH)2D or fibroblast growth factor 23 (FGF23) can inhibit PTH secretion." (PMID 39829956, 2024). "The main differential diagnoses of hypocalcemia with hyperphosphatemia and high PTH, with normal renal function, include PHP and VDD." (PMID 39350885, 2024). "Hypoparathyroidism following thyroidectomy is characterized by low levels of PTH, leading to hypocalcemia." (PMID 39258042, 2024). "Postoperative hypocalcemia is a common complication due to the abrupt drop in PTH levels and pre-existing bone disease from long-standing hyperparathyroidism." (PMID 39478762, 2024). "Low magnesium levels can lead to hypoparathyroidism, resulting in hypocalcemia, which stimulates parathyroid hormone secretion and promotes bone resorption, thereby disrupting the balance of bone metabolism." (PMID 38892573, 2024). "In most studies (18 of 23), the hypoPT diagnosis was confirmed by laboratory parameters, namely low or inappropriately low PTH levels in combination with hypocalcemia or low calcium levels for at least six months." (PMID 38578400, 2024). "Cinacalcet is a calcimimetic widely used as a therapy to reduce parathyroid hormone levels in the adult population, with hypocalcemia among its side effects." (PMID 37964112, 2024). "The European Society of Endocrinology clinical guideline defines hypoparathyroidism as having hypocalcemia (ionic Ca2+ < 4.61 mg/dL), abnormally low parathormone (PTH) levels, or requirement for ongoing active vitamin D therapy." (PMID 38472977, 2024). "The phenotype includes hypocalcemia and hyperphosphatemia, both due to proximal renal tubular resistance to PTH and an Albright Hereditary Osteodystrophy (AHO)." (PMID 39267114, 2024). "First, 1,25(OH)2D significantly prevents sudden, severe postoperative hypocalcemia due to decreased PTH levels." (PMID 38803480, 2024). "A recent meta-analysis comparing various calcimimetics has shown that Etelcalcetide is the most efficacious calcimimetic agent for lowering serum PTH levels but highlighted side effects such as hypocalcemia, nausea, and vomiting." (PMID 39407947, 2024). "Permanent hypoparathyroidism (PH) was defined as having parathyroid hormone levels going below the reference value at the time point of postoperative counseling and showing hypocalcemia continuing more than 12 months post-thyroidectomy." (PMID 39590119, 2024). "In dialysis patients, persistent hypocalcemia and hyperphosphatemia lead to osteitis fibrosa which is characterized by elevated PTH level." (PMID 39364464, 2024). "A high 1,25(OH)2D level was the most important preoperative factor for hypocalcemia (<2 mmol/L; p<0.05) on the first postoperative day; however, only PTH decrease was statistically significant (p<0.001) when intraoperative factors were added." (PMID 38803480, 2024). "Firstly, parathyroid failure after thyroidectomy is defined as PTH ≤10 pg/mL with hypocalcemia symptoms." (PMID 38646308, 2024). "Both hypocalcemia and hyperphosphatemia stimulate hypertrophy of the parathyroid gland and result in increased production and secretion of parathyroid hormone." (PMID 39310569, 2024).